TLR4 (toll like receptor 4)
Diseases named in the same sentence as TLR4 in open-access papers (continued):
Sharing a sentence is not in itself a finding about the gene and the disease.
cancer (continued). "Conversely, in HPV-negative cases, TLR4 hyperactivation leads to the activation of inflammatory pathways related to increasing cell proliferation, apoptosis inhibition, lymphatic and vascular neo-angiogenesis, and metastasis, favoring a “deviated” cancer-related inflammatory microenvironment." (PMID 39451550, 2024). "However, several studies have demonstrated a role of TLR4 in the pathogenesis of cancer." (PMID 38593176, 2024). "Additionally, TLR4 is known to play a crucial role in the regulation of glycolysis and pyruvate oxidation decarboxylation, with its expression being upregulated in various types of cancer." (PMID 38689341, 2024). "MPLA is a TLR4 agonist modified from lipid A, the biologically active part of Gram-negative bacterial LPS endotoxin; compared to LPS, MPLA exerts similar immunostimulatory activity but with reduced toxicity and has been approved by the FDA to use against cancer-causing HPV." (PMID 36765715, 2023). "Moreover, our study demonstrated that RPLP2 interacts with TLR4 to promote cancer development." (PMID 38052785, 2023). "Notably, emerging research suggests that TLR4 also exerts a regulatory role in various cancers." (PMID 37896221, 2023). "Besides ccRCC, we also examined whether TLR4 expression has a potential in predicting prognosis in other cancers." (PMID 37576399, 2023). "Thus, TLR-4 agonists have been widely studied as potential agents for cancer immunotherapy." (PMID 37103820, 2023). "In this direction, TLR4 signaling could be exploited to improve HCC cancer vaccines." (PMID 37345131, 2023). "Indeed, both pSTAT3 and TLR4 are important inducers of PD-L1 expression on cancer cells." (PMID 35205801, 2022). "An alternative strategy may be to use TLR4 agonists as cancer vaccine adjuvants." (PMID 35163998, 2022). "Importantly, cancer invasion induced by TLR4 stimulation was markedly enhanced in USP15KO A549 cells treated with LPS, whereas it was inhibited by co-treatment of LPS with 3-MA or CQ (LPS vs. vehicle, or LPS + 3-MA and LPS + CQ vs. LPS in Ctrl A549 and USP15KO A549)." (PMID 35422093, 2022). "Lentinan (LNT) could inhibit the growth of cancer cells by targeting toll-like receptor-4 (TLR4)." (PMID 36290687, 2022). "However, there are fewer studies on clinical efficacy, and further research is needed to determine whether the TLR4 gene can be a breakthrough in cancer treatment in the future." (PMID 36281200, 2022). "Murine and human cancer cells including lung, pancreatic, colon and gastric cancer constitutively release high levels of Hsp70 and Hsp90 as surface proteins on extracellular vesicles (EVs), which induce muscle wasting by directly activating TLR4 on muscle cells." (PMID 34950660, 2021). "With respect to the immune system, RFX1 acts as an activator of MHC Class II genes and represses MCP1, CD11a, CD70, IL17A, TLR4, and the TGFβ2 expressions, which could be instrumental in understanding etiology and materializing treatment strategies for cancer and other immune-related disorders." (PMID 33964962, 2021). "However, they do mention that some TLR4 antagonists including Eritoran and TAK242 (both proposed here) were used successfully in the treatment of inflammation associated with cancer, rheumatoid arthritis, and other inflammatory diseases (and references therein)." (PMID 33505220, 2021). "Finally, TLR4 gene expression and OS-related cancer types were screened for further study." (PMID 34631699, 2021). "Parabacteroides was reported to have anti-inflammatory and anti-cancer properties by the suppression of Toll-like receptor 4 (TLR4) and protein kinase B (Akt) signaling and the promotion of apoptosis process, indicating that Parabacteroides might be related to diseases defense." (PMID 34466688, 2021). "Therefore, TLR4 antagonists and also the negative regulator of the adapter complex may be the novel therapeutics for cancer treatments." (PMID 34385421, 2021).
cancer (continued). "Chronic TLR4 activation promotes an inflammatory environment conducive to carcinogenesis, but TLR4 is necessary to the elimination of dying cancer cells upon radio or chemotherapy and perioperative treatment with a TLR4 agonist in rats and mice reduces cancer metastasis." (PMID 35004315, 2021). "In the literature, it was shown, that the GTPase Rab7, which is currently gaining importance as an oncosuppressor, impairs TLR4 by promoting its lysosomal degradation and may therefore play a role in immune-suppressive mechanisms during cancer progression and cachexia development." (PMID 34630405, 2021). "Therefore, TLR4-based cancer immunotherapy has received great attention." (PMID 33841142, 2021). "Consequently, this present study aimed to address whether the suppression of LPS-mediate TLR4-signaling reduce inflammation-induced cancer progression in addition to dampen the inflammatory response." (PMID 32492880, 2020). "In addition, TLR4/NF‐κB signaling pathway plays an important role in cancer development." (PMID 32750218, 2020). "In addition, TLR4-negative cells such as human embryonic kidney HEK293 cells have been presented as an in vitro cellular model for the investigation of biological effects mediated through TLR4 receptor in comparison with TLR4-positive cells, and for drug and anti-cancer agent screening." (PMID 32448225, 2020). "Interestingly, p62-deficient cancer cells, p62-knockdown (p62KD) SK-HEP-1, p62KD MDA-MB-231, and p62-knockout (p62KO) A549 cells, exhibited increases in autophagic activation, and cancer cell migration/invasion induced by TLR4 stimulation." (PMID 32384667, 2020). "Additionally, the activation of TLR4/MyD88 results in Sp1 accumulation in cancer progression." (PMID 32144747, 2020). "Interestingly, TLR-4 is the most popular among the TLRs evaluated as receptors in numerous clinical trials as a potential target for immunotherapy against various pathologies concerning inflammation, viral infection, immune diseases, and cancers." (PMID 32354122, 2020). "Interestingly, in follicular thyroid neoplasms, both the downregulation and upregulation of TLR4 have been connected to primary metastases and the aggressiveness of cancer, whereas TLR2 expression associated with no clinicopathological parameter." (PMID 32424768, 2020). "Interestingly, the role of TLR4 in cancer-induced muscle catabolism appears relatively specific." (PMID 31480237, 2019). "It seems that the Toll-like receptor 4 (TLR4)/myeloid differentiation factor 88 (Myd88) signaling pathway is the major enhancer of the immunosuppressive activities of MDSCs and consequently induces immunosuppression, e.g., in conditions such as infections and cancers." (PMID 31129755, 2019). "In the context of cancer, this role of Hb could support metastatic growth through the activation of NF-κB in TLR4 positive cancer cells, or through the activation of local tissue cells wherein effective anti-cancer immune functions are sacrificed in lieu of tissue inflammation and healing." (PMID 31163699, 2019). "However, excessive activation of TLR4 may enhance not only immune response but also gives rise to cancer progression through disruption of intestinal immune homeostasis." (PMID 31157230, 2019). "In addition to increased cell survival and proliferation, TLR4 activation on breast and cancer cells can release factors (such as MMPs, NO, VEGF, IL-6, and IL-12) and ligands (such as B7-H1 and B7-H2) which are responsible for immune evasion of cancerous cells." (PMID 31480568, 2019). "Therefore, TLR-4-TRIF-NF-κB signalling might be a conserved mechanism mediating cancer cell debris-induced IL-1β production in M2 polarised macrophages." (PMID 31588122, 2019). "Finally, the effect of the DC-based cancer vaccine was assessed using wild type and TLR4−/− BMDCs to see whether its adjuvant effects are dependent on TLR4." (PMID 30819254, 2019).
cancer (continued). "The identification of Mettl3, as a positive regulator of DC function and TLR4 signaling, may have great relevance to the pathogenesis of diseases related with DC dysfunction, and may facilitate cancer immunotherapy, such as adoptive infusion of DC vaccine or design of potent cellular adjuvant." (PMID 31015515, 2019). "A role of TLR4 in cancer progression might be somewhat controversial." (PMID 28212583, 2017). "Thus, we tested the hypothesis that TLR4 is a key mediator of cancer-induced muscle wasting due to its integration of catabolic signaling through activating muscle protein degradation pathways directly and increasing cytokine release indirectly." (PMID 28536426, 2017). "On the other hand, whether cytokine increase in cancer patients is dependent on TLR4 is unknown." (PMID 28536426, 2017). "However, whether expression of TLR4 in NSCLC cancer tissue could be identified as a prognostic marker needs to be investigated." (PMID 28484456, 2017). "However, the detailed mechanism through which TLR4 mediates cancer-induced muscle wasting remains unknown." (PMID 28536426, 2017). "Thus, the up-regulation of OPN expression by TLR4 signal may be an important factor that could enhance proliferation and metastasis ability of cancer cells." (PMID 29228698, 2017). "In addition, screening cancer patients for SNPs in TLR4 and P2RX7 could help identify patients who may benefit from additional therapeutic interventions to overcome these mutations." (PMID 26486085, 2015). "To date, two meta-analyses have been published on TLR4 polymorphisms and risk of cancer in general, but no meta-analyses have been published addressing the association between these and the other selected polymorphisms in the current study and the risk of GC in particular." (PMID 23565226, 2013). "Furthermore, higher rates of TLR4 and CXCR7 expression were found in human PTC tissues than in normal thyroid tissues, indicating that expression of these two molecules is associated with increased carcinoma growth and metastasis potential in human PTC." (PMID 24363762, 2013). "However, the association between TLR4/MyD88 signalling and cancer mortality has not been well investigated in clinical samples." (PMID 22533866, 2012). "The Kaplan-Meier analysis shows that the HCC patients with high TLR4 expression in general had a shorter cancer-free interval and a worse overall survival than those with low expression, suggesting that TLR4 may be a useful biomarker of HCC metastasis and recurrence." (PMID 22938142, 2012). "Our investigation focused on gene expression of TLR4, DC-SIGN, NF-κB, and BCL2 in healthy and cancer control groups." (PMID 42138288, 2026). "The specific signaling pathways involved vary by cancer type, including JAK2/STAT3, TLR4/MyD88, miR-195-5p/FGFR1, PADI3-ERK, ERK/GSK3β, AKT/mTOR, and the Toll-Like Receptor 4-Mediated Nuclear Factor-κB Signaling Pathways." (PMID 41599296, 2026). "For instance, TLR4-mediated signaling has been shown to promote EMT, a process that endows cancer cells with increased motility and resistance to apoptosis." (PMID 41332426, 2025). "LPS-induced TLR4 signaling influenced the NF-Kappa B, MAPK, ERK, and JNK pathways, which in turn enhanced the survival and growth of cancer cells." (PMID 40666174, 2025). "Researchers have demonstrated that following wogonin treatment, the TLR4/NF‐κB signaling pathway suppressed AMD (Age‐related macular degeneration), which can lead to the development of cancers." (PMID 41164269, 2025). "Toll-like receptor 4 (TLR4), a critical component of innate immunity, is often dysregulated in cancer, contributing to inflammation, enhanced cell proliferation, and inhibition of apoptosis." (PMID 40430191, 2025). "Extracellular HMGB1 interacts with receptors, such as toll-like receptor 4 and receptor for advanced glycation end products (RAGE), promoting cell proliferation, survival, and migration in cancer cells." (PMID 40389855, 2025).
cancer (continued). "These include their overexpression in cancer tissues, presence in extracellular compartments, and involvement in ligand-receptor interactions—such as with RAGE and Toll-like receptor 4 (TLR4)—that can be disrupted by small molecules or monoclonal antibodies." (PMID 41404073, 2025). "Previous studies have shown that under hypoxic conditions in hepatocellular carcinoma, HMGB1 can be passively released and induce caspase-1 activation through activation of TLR4 and RAGE signaling pathways, thus promoting cancer cell invasion and metastasis." (PMID 40969278, 2025). "The expression of TLR4 promotes the secretion of cancer‐promoting factors by macrophages, including IL‐6, IL‐23p23, and TNF‐α, enhancing inflammation and cancer growth." (PMID 40547943, 2025). "The TLR-4-mediated pathway controls IL-6 and IL-8 production and induces anti-apoptotic protein XIAP in cancer cells, leading to PTX resistance." (PMID 40404908, 2025). "In conclusion, S100A9 is capable of binding to certain receptors, including TLR4, RAGE, and MCAM, through which it can trigger specific pathways which can then stimulate cancer cell proliferation, metastases, and malignancy." (PMID 41009692, 2025). "LPS is a component of Gram-negative bacteria and a potent inducer of innate immune responses via Toll-like receptor 4 (TLR4) signaling, and increased response to LPS is often observed in chronic inflammatory models, including cancer." (PMID 40992926, 2025). "Mechanistically, LPS activates the TLR4 signaling pathway to facilitate immune suppression factors, such as TGF-β, VEGF, and IL-8, aiding the immune escape of cancer cells." (PMID 40444051, 2025). "Recently, using an in vitro EC model, it was demonstrated that heme metabolism reduces phagocytosis by modulating the secretion of TLR4-mediated IFN Iα as well as CD36 expression; contributing to events leading to immune escape in this cancer." (PMID 40871563, 2025). "Mechanistically, we found that miR-3124-5p secreted by CAFs exerts a pro-cancer effect by inhibiting TOLLIP expression and promoting the TLR4/MyD88/NF-κB signaling pathway." (PMID 39735680, 2025). "Receptors of S100A9, including TLR4, RAGE, CD147, MCAM and NPTN are expressed in multiple cell types, such as cancer cells, MDSCs, macrophages and NK cells." (PMID 38713229, 2024). "Of the many subtypes of TLRs, TLR4 is highly expressed on several types of PDAC cells, and its expression correlates with the invasiveness of cancer cells." (PMID 39518973, 2024). "In pan-cancer, HMGB1 had the highest positive correlation with NUDT21, followed by TLR4, CD276, and TNFRSF4." (PMID 38349866, 2024). "There was a significant reduction in cellular migration of U87 cancer cells at TLR3 and TLR4 preconditioning." (PMID 38698968, 2024). "It was shown that the expression of TLR-2, TLR-4, and TLR-7 mRNA and their protein levels were significantly higher in cancer tissues compared to control tissues (p < 0.05)." (PMID 39451226, 2024). "The toll-like receptor 4 (TLR4) signaling pathway constitutes an intricate network of protein interactions primarily involved in inflammation and cancer." (PMID 38930793, 2024). "However, PTX-mediated modulation of the TLR4 pathway is implicated in the activation of NF-κB and MAPK-related downstream signaling and subsequent release of pro-inflammatory molecules that enhance the progression of cancers and confer chemoresistance to drug intervention in cancers." (PMID 38291541, 2024). "TLR4 activation in HCC enhances tumor growth through multiple signaling pathways, including MAPK, NF-κB, and PI3K/AKT, contributing to cancer cell proliferation and survival." (PMID 39335657, 2024). "Knockdown of TLR4 results in reduced expression of ACAT1, and subsequently leads to a decrease in cancer cell proliferation, highlighting the involvement of TLR4 in modulating tumorigenesis and progression." (PMID 38930793, 2024).
cancer (continued). "In response to HMGB1 released by dying cancer cells, macrophages produce proinflammatory cytokines, such as IL-6 and TNF, via the Toll-like receptor 4-mediated pathway." (PMID 38474078, 2024). "Toll-like receptors, TLR-4 and TLR-2 are present on a variety of immune cells i.e. NK cells, macrophages and some cancer cells." (PMID 39050853, 2024). "Briefly, enhancement of cancer cell proliferation, establishment of a cancer‐promoting immune environment through miRNA‐mediated activation of TLR2/TLR4, and the evasion of immune checkpoints have been proposed as its main mechanisms." (PMID 38775019, 2024). "The ability of Dt to trigger immunomodulation in cancer cells was previously predicted by the significant binding affinity and pose between Dt and two selected proteins, FCGR1A, and TLR4." (PMID 36829917, 2023). "Normally, LPS acts on its specific receptor, named Toll-like receptor 4 or TLR4, located on the cell membrane of several cell types, especially in cancer cells." (PMID 37509740, 2023). "Icariside II showed inhibition of cancer cell apoptosis by inhibition of STAT3 and TLR4-MyD88-ERK signaling in response to these chemotherapeutic agents." (PMID 37743502, 2023). "Bacterial lipopolysaccharides (LPS) are potent innate immunostimulants targeting the Toll-like receptor 4 (TLR4), an attractive and validated target for immunostimulation in cancer therapy." (PMID 37223101, 2023). "Four immune checkpoint proteins, PD-L1, TLR4, HLA-G, and NKG2A, belong to the TMEM family and can form homodimers or heterodimers to regulate cancer immunotherapy." (PMID 37103820, 2023). "According to studies on tumors, LPS has been shown to activate TLR4 in cancer cells, which then activates NF-κB, JNK, and MAPK signals, enhancing the cancer cells’ propensity for invasion and migration." (PMID 37188204, 2023). "They showed that 10 Gy irradiation of cancer cell lines (U2OS, A549, HEPG2 and MCF7) increased the expression of TLR2, TLR3, TLR4, TLR6 and TLR9." (PMID 37112730, 2023). "The results showed that cancer cells are characterized by lower expression levels of TLR4, TGF-β1, IFN-γ, and TNF-α, and that TLR4 expression was identical in low- and high-grade cancer." (PMID 40778061, 2023). "TLR4 is a special member of the TLR family, particularly in the context of cardiovascular disease and cancer." (PMID 36733418, 2023). "The major signal transduction axis of HMGB1 in cancer seems to be mediated through the receptor for advanced glycation end products (RAGE) and toll-like receptor (TLR)-4." (PMID 37511951, 2023). "The secretion of the HSP90 cochaperone protein Morgana induces cancer cell migration by activating TLR2, TLR4, and LRP1." (PMID 38052785, 2023). "Since TLR4 is potentially the most efficacious PRR in regulating the growth and progression of various cancers, several TLR4-modulating molecules have been developed so far." (PMID 37822929, 2023). "The chronic inflammation inspired by TLR4 and CAP1 is involved in the malignancy process, as is the overexpression of TLR4 and CAP1 in the TME, contributing to the progression of cancer." (PMID 35875143, 2022). "Of the numerous TLR subtypes, TLR4 is overexpressed on PDAC and its expression correlates with cancer invasiveness." (PMID 36232715, 2022). "TLR agonists approved by the FDA for the treatment in cancer patients include Bacillus Calmette-Guérin (BCG) (activates TLR2, TLR3, TLR4 and TLR9), monophosphoryl lipid (MPL) (TLR4 agonist) and imiquimod (TLR7 agonist)." (PMID 36365103, 2022). "S100A8-A9 heterodimer mainly stimulates downstream cascades through two receptors: toll-like receptor 4 (TLR4) and receptor for advanced glycation end products (RAGE), and both of them are widely reported to impact cancer immunity." (PMID 35440136, 2022). "When activated, they enhance the production of MMP9 via the TLR4/MYD88/NF-κB/AP-1 axis and increase the tumorigenic potential of cancer cells, promoting their immune evasion." (PMID 35406619, 2022).